HDAC6 (histone deacetylase 6)
Diseases named in the same sentence as HDAC6 in open-access papers (continued):
Sharing a sentence is not in itself a finding about the gene and the disease.
diffuse large B-cell lymphoma (9 papers, 2008 to 2025). "HDAC6 shows aberrant expression in diffuse large B-cell lymphoma (DLBCL)." (PMID 36076996, 2022). "In contrast, immunohistochemistry (IHC) analysis revealed that in diffuse large B-cell lymphoma (DLBCL) and breast cancer, high HDAC6 expression correlated with better overall, progression-free and disease-free survival, respectively; and overall survival in high-grade serous ovarian cancer (HGSOC)." (PMID 36012642, 2022). "Expression of HDAC1, HDAC2, and HDAC6 was significantly upregulated in PTCL and diffuse large B-cell lymphoma, and HDAC6 levels indicate a favorable prognosis." (PMID 34512154, 2021). "Only 4% of primary diffuse large B cell lymphomas (DLBCL) and 18% of HL cases demonstrated detectable levels of HDAC6." (PMID 30096875, 2018). "Jia et al46 demonstrated that histone deacetylase 6 regulated miR‐27b that suppressed proliferation, promoted apoptosis, and targeted oncogenic MET, implicating the potential application of miR‐27b for prognostic prediction and therapy of diffuse large B‐cell lymphoma." (PMID 30973209, 2019). "Overexpression of HDAC1, HDAC2, and HDAC6 and of higher acetylation levels of histone H4, with respect to the normal lymphoid tissue, have been reported by immunohistochemical studies conducted in patients with peripheral T-cell lymphoma (PTCL), and diffuse B large cell lymphoma (DLBCL)." (PMID 30096875, 2018).
ischemic stroke (9 papers, 2016 to 2025). A stroke disorder caused by obstruction of blood flow to the brain, due to thrombotic (local blood clot formation) or embolic (due to a blood clot or other material traveling from another site) event. "Therefore, HDAC6 inhibition may be the underlying mechanism by which USC‐Exos–induced neurogenesis in ischaemic stroke." (PMID 31667951, 2020). "Here, we discovered that genetic ablation or pharmacological inhibition of HDAC6 reduced brain injury after ischemic stroke by increasing macrophage migration inhibitory factor (MIF) acetylation." (PMID 35585040, 2022). "Histone deacetylase 6 (HDAC6) is a promising target for neuroprotection in many neurological disorders, including ischemic stroke." (PMID 35585040, 2022). "Our results indicate that increased MIF K78 acetylation contributes to the neuroprotective effect of HDAC6 inhibitors in ischemic stroke." (PMID 35585040, 2022). "Our study found that the expression of HDAC6 significantly increased both in vitro and in vivo ischaemic stroke models." (PMID 31667951, 2020). "In this study, we investigated the effects of USC‐Exos on neurogenesis in ischaemic stroke models, as well as the relationship between HDAC6 expression and USC‐Exos–induced neurogenesis." (PMID 31667951, 2020). "Our findings suggest that HDAC6 is a promising target for the treatment of ischemic stroke, and clinical trials of TubA for this brain disorder are warranted." (PMID 26790818, 2016). "After ischemic stroke, both Hdac6 mRNA and HDAC6 protein levels were increased in the cortex." (PMID 35585040, 2022). "Moreover, the MIF K78R mutant reversed the protective effect of HDAC6 inhibition and aspirin treatment in response to ischemic stroke." (PMID 35585040, 2022). "In fact, HDAC6 (histone deacetylase 6, a multidomain cytosolic enzyme with α-tubulin deacetylase activity) is increased in AD and HD, and dysregulation of HDACs also take part in ischemic strokes." (PMID 34776926, 2021). "In addition, a pharmacological or genetic suppression of HDAC6 was performed to evaluate the functional significance of HDAC6 in the pathology of ischemic stroke induced deficits." (PMID 30999900, 2019). "However, the mechanism by which HDAC6 inhibition protects neurons after ischemic stroke remains unclear." (PMID 35585040, 2022). "We then investigated the relationship between HDAC6 expression and the effects of USC‐Exos–induced pro‐neurogenesis activity in ischaemic stroke." (PMID 31667951, 2020). "Our results indicate that the neuroprotective effect of HDAC6 inhibition and aspirin treatment results from MIF K78 acetylation; thus, MIF K78 acetylation may be a therapeutic target for ischemic stroke and other neurological diseases." (PMID 35585040, 2022). "HDAC6 is known to deacetylate non-histone proteins, such as macrophage migration inhibitory factor (MIF), and its inhibition by TubA markedly increases MIF acetylation, a modification that contributes to its neuroprotective function in ischemic stroke models." (PMID 40867911, 2025).
Parkinson (9 papers, 2013 to 2024). "Further analysis will aim to provide new insights into the complex role of the HDAC6 phosphorylation in controlling neurodegeneration in PD and parkinsonism." (PMID 32655357, 2020).
acute lymphoblastic leukemia (8 papers, 2013 to 2026). Leukemia with an acute onset, characterized by the presence of lymphoblasts in the bone marrow and the peripheral blood. "To evaluate the effect of the selective HDAC6 inhibitor WT161 on acute lymphoblastic leukemia (ALL), we first examined HDAC6 expression in four ALL cell lines (BALL-1, NALM-6, Jurkat, and MOLT-4)." (PMID 41249257, 2025). "Notably, RNase T2 upregulation upon HDAC6 loss was observed in myeloid leukemia cells but not in lymphoblastic leukemia cells." (PMID 41794832, 2026). "In T-cell acute lymphoblastic leukemia (T-ALL), SUZ12 mutations activate oncogenic signaling pathways, increasing sensitivity to HDAC6 inhibitors." (PMID 40949882, 2025). "Tubacin, a selective HDAC6 inhibitor, has been reported to have anti-proliferative effects and induce apoptosis in acute lymphoblastic leukemia (ALL) cells." (PMID 23758695, 2013).
bladder cancer (8 papers, 2018 to 2024). "Because SIRT2 has also been suggested to be involved in cortactin deacetylation in A549 cells and work synergistically with HDAC6 to promote cell migration and invasion in bladder cancer, we examined the role of SIRT2 in dendrite development in vitro." (PMID 32711564, 2020). "It has been shown that a significant number of bladder cancer cell lines are characterized by downregulated HDAC6 mRNA levels, although the cognate protein is presented with a notably varying expression among them." (PMID 30875794, 2019). "Moreover, several studies have reported a relationship between HDAC6 and tumours, and HDAC6 is overexpressed in bladder cancer and lung cancer." (PMID 32107418, 2020). "However, in a recent study, HDAC6 inhibition in RT112 bladder cancer cells by tubacin resulted in induction of apoptosis and proliferation arrest, which was associated with the downregulation of FGFR3, MYC and Cyclin D1, and DNA-damage induction." (PMID 30875794, 2019). "HDAC6 has been previously shown to act synergistically with SIRT2, in promoting bladder cancer-cell migration and invasion, by targeting the cytoskeletal protein Cortactin in the cell line BLX211." (PMID 30875794, 2019). "As one of the odd-chain fatty acids, Nonanoic acid (C9:0) was found to inhibit the expression of HDAC6, which result in an anti-cancer proliferation effect; again, the detailed mechanism needs to be confirmed in bladder cancer." (PMID 36005168, 2022). "Altogether, it seems that bladder carcinomas may not critically depend on HDAC6 expression for cell survival and growth." (PMID 30875794, 2019). "Importantly, the siRNA-mediated reduction of HDAC6 protein contents in bladder cancer cells could not induce apoptotic death and diminished viability." (PMID 30875794, 2019).
Cerebral ischemia (8 papers, 2015 to 2023). Restriction of arterial blood supply to the brain associated with insufficient oxygenation to support the metabolic requirements of the tissue. "Task-specific motor rehabilitation combined with enriched enrichment promotes neural regeneration and maturation of new neuronal dendrites by reversing histone deacetylase 6 (HDAC6) dysfunction caused by cerebral ischemia." (PMID 37484824, 2023). "Tubacin, a selective HDAC6 inhibitor, was found to alleviate ischemic brain injury in T2D mice with focal cerebral ischemia by endorsing eNOS expression in an HDAC6-dependent mechanism." (PMID 34071497, 2021). "Depending on the BAG1/BAG3 ratio and expression level of HDAC6, a switch from the ubiquitin-proteasome pathway to the autophagy-lysosome pathway occurs between 10 and 30 min during cerebral ischemia." (PMID 32089771, 2020). "Selective knockdown of HDAC6 by shRNA has been shown to protect mouse cortical neurons from oxygen and glucose deprivation, an in vitro cerebral ischemia model." (PMID 26790818, 2016). "However, further efforts are still needed to develop novel HDAC6 inhibitors for disorders whose etiology is based upon cerebral ischemia-reperfusion injury." (PMID 31354911, 2019). "HDAC6 is upregulated in a Rett syndrome model, has a negative effect on BDNF trafficking, and is involved in T-cell regulation in neuroinflammation after brain ischemia." (PMID 34638996, 2021).
cyst (8 papers, 2012 to 2023). A sac-like closed membranous structure that may be empty or contain fluid or amorphous material. "HDAC6 is upregulated in Pkd1 mutant mouse cells and was found to activate factors associated with cyst growth, such as EGFR." (PMID 35847973, 2022). "HDAC6 is upregulated in mutant mouse Pkd1 cells and activates a number of different factors associated with cyst growth, such as EGFR and EGF-induced β-catenin nuclear localisation." (PMID 34948126, 2021). "HDAC6 has been recognized to exacerbate cyst growth in ADPKD through enhancing cAMP signaling and upregulating epidermal growth factor receptor (EGFR) activity." (PMID 37152951, 2023). "Inhibition of HDAC6 with tubacin attenuated cyst growth and improved kidney function through cAMP signaling by preventing Ca2+ efflux from the endoplasmic reticulum." (PMID 35847973, 2022). "Inhibition of HDAC6 prevents the release of Ca2+ from the endoplasmic reticulum, consequentially attenuating cyst growth through cAMP signalling." (PMID 34948126, 2021). "Aberrant HDAC6 activity is a factor in cyst growth and inhibitors of this enzyme are thought to retard cystogenesis." (PMID 34250905, 2021). "Consistently, Yanda and colleagues also found that treatment with ACY-1215, a specific HDAC6 inhibitor, slowed cyst growth in a mouse model of ADPKD by lowering cAMP levels." (PMID 30134806, 2018). "Collectively, HDAC6 contributes to cyst growth by promoting cell proliferation and fluid secretion induced by aberrant Ca2+ signalling, abnormal cAMP signalling, and prolonged EGFR signalling." (PMID 30134806, 2018). "Tubacin treatment reduced the cell number and Ki67 staining, a marker of proliferation, in each Shp2-E76G cyst to the level similar to WT Shp2 cyst, suggesting that HDAC6 inhibition resets the normal growth in 3D culture." (PMID 26783207, 2016). "To test whether inhibition of HDAC6 reduces cystic cell proliferation and cyst growth, we treated fish with tubastatin A, an HDAC6 inhibitor." (PMID 34545930, 2021). "Nonetheless, HDAC6 inhibitors have been used by other groups to target cyst size." (PMID 34250905, 2021). "HDAC6 promotes cyst formation and disease by enhancing intracellular cAMP in ADPKD." (PMID 30134806, 2018). "We suspected that upregulated HDAC6 might also contribute to the mislocalization of the apical EGFR on cyst lining epithelia." (PMID 23152903, 2012). "Therefore, we reasoned that pharmacologically targeting HDAC6 with relatively selective inhibitors may reduce cyst formation in cellular models of ADPKD." (PMID 34250905, 2021). "Thus, these authors suggested that Pkd1 mutation-induced upregulation of HDAC6 might slow the trafficking of EGFR from early endosomes to late endosomes along microtubules for degradation through deacetylation of α-tubulin, leading to phosphorylation of ERK1/2 to facilitate cyst formation." (PMID 30134806, 2018).
gastric cancer (8 papers, 2020 to 2025). A primary or metastatic malignant neoplasm involving the stomach. "HDAC6 is frequently overexpressed in various malignancies, including primary acute myeloid leukemia, gastric cancer, breast cancer, ovarian cancer, and colorectal cancer, and is strongly associated with unfavorable prognosis." (PMID 40115907, 2025). "HDAC6 inhibition can lead to apoptosis in gastric cancer cells." (PMID 38920983, 2024). "Furthermore, HDAC6 inhibition can block the process of proliferation and invasion of gastric cancer cells." (PMID 36457493, 2022). "All in all, canagliflozin was identified to target HDAC6 and served as a potent HDAC6 inhibitor, and it may be developed as potential therapeutics for gastric cancer." (PMID 36457493, 2022). "Although more and more studies reveal that HDAC6 may serve as an oncogene in gastric cancer, few HDAC6 inhibitors are selected for gastric cancer treatment, especially for metastasis." (PMID 36457493, 2022). "However, in gastric cancer, PTBP3 promotes metastasis of gastric cancer by regulating CAV1 and reduces the sensitivity of gastric cancer cells to 5-Fu by the HDAC6/Akt/TYMS pathway." (PMID 32477006, 2020). "Collectively, our data revealed that canagliflozin inhibits gastric cancer cell migration and EMT through targeting HDAC6 in vitro and in vivo." (PMID 36457493, 2022). "Thus, targeting HDAC6 could be a promising therapeutic option for gastric cancer treatment." (PMID 36457493, 2022). "We also demonstrated that canagliflozin can blocks the process of EMT and cell migration through the inactivation of HDAC6 in MGC-803 and HGC-27 gastric cancer cells in vitro." (PMID 36457493, 2022). "HDAC6 downregulation inhibited gastric cancer cell growth without affecting cell cycle transition or the processing of cell death." (PMID 36076996, 2022). "HDAC6 enables α-tubulin deacetylation in hypoxic conditions, allowing EMT factor, SMAD3, to translocate to the nucleus; HDAC6 inhibitors have been shown to inhibit metastasis in TNBC and angiogenesis in gastric cancer cells by reducing HIF-1α and VEGF levels." (PMID 33808542, 2021). "Previously, we demonstrated that andrographolide suppresses the lytic reactivation of EBV in gastric cancer cell lines by attenuating the expression of host transcription factors, SP1 and MEF2, via epigenetic modifications, especially through the function of HDAC6 and DNMT3A." (PMID 37958849, 2023). "HDAC6 is mostly located in the cytoplasm to deacetylate non-histone substrates, which has been identified as a critical promoter of many oncogenic pathways in cancers, including gastric cancer." (PMID 36457493, 2022).
Obesity (8 papers, 2022 to 2025). Accumulation of substantial excess body fat. "This can also prove that EGR3 can work as an important regulator of rhythm disturbance leading to the development of obesity, which can inhibit adipogenesis through HDAC6." (PMID 38467615, 2024). "We summarized some potential new protein targets associated with obesity that exacerbate influenza infection in respiratory disease, including α/β-hydrolase domain 6, Histone deacetylase 6, G-protein-coupled receptor 4, and so on, which can affect obesity and influenza." (PMID 40863240, 2025). "(I–K) HDAC6 KO or wild-type mice were fed HFD to induce obesity." (PMID 35323110, 2022). "HDAC6 deficiency may lead to enhanced activation of CD4+ and CD8+ T cells and imbalance of the gut microbiota; accordingly, the representation of the S24–7 family and Lactobacillus decreases, Bacteroides and Parabacteroides abundances increase, which promotes obesity." (PMID 35662937, 2022).
oral squamous cell carcinoma (8 papers, 2008 to 2025). "Dysregulation of HDAC6 deacetylase activity and HDAC6 overexpression have both been associated with therapy resistance in several solid cancers, including oral squamous cell carcinoma." (PMID 39800760, 2025). "High protein and mRNA levels of HDAC6 are detected in oral squamous cell carcinoma (OSCC), and inhibition of HDAC6 synergistically induces autophagy and apoptosis together with Bortezomib in HNSCC." (PMID 32961679, 2020).
pulmonary hypertension (8 papers, 2017 to 2024). Increased pressure within the pulmonary circulation due to lung or heart disorder. "Therefore, HDAC6 deficient mice had some protective effect against pulmonary hypertension caused by chronic hypoxia." (PMID 35752619, 2022). "Moreover, Hdac6 deficient mice were partially protected against chronic hypoxia-induced pulmonary hypertension." (PMID 28674407, 2017). "Pharmacological inhibition of HDAC6 reduced pulmonary artery pressure and vascular resistance in monocrotaline and Sugen-hypoxia rat models of PAH and mice deficient in HDAC6 showed attenuation of chronic hypoxic pulmonary hypertension." (PMID 34068984, 2021). "Pharmacological inhibition of HDAC6 attenuates pulmonary hypertension by decreasing total pulmonary vascular resistance (TPR), cardiac output (CO), mean PA pressure (mPAP), and RV systolic pressure (RVSP)." (PMID 37461108, 2023). "In pulmonary hypertension, Boucherat and colleagues have shown that increased HDAC6 maintains the protein Ku70 in a hypoacetylated state, blocking the translocation of Bax to mitochondria and preventing apoptosis." (PMID 34068984, 2021). "Inhibition of HDAC6 could reduce the proliferation and anti-apoptotic ability of pulmonary smooth muscle cells with pulmonary hypertension." (PMID 35752619, 2022). "Furthermore, Hdac6 knockout mice were partly protected from pulmonary hypertension induced by chronic hypoxia." (PMID 35052850, 2022). "Taken together, these results suggest that HDAC6 may regulate VC in aortic valve disease and pulmonary arterial hypertension." (PMID 32375326, 2020). "In the pulmonary artery smooth muscle cells (PASMCs) of patients with pulmonary arterial hypertension (PAH), HDAC6 expression level was significantly upregulated, and inhibition of HDAC6 could reduce PASMC proliferation and resistance to apoptosis and finally improve established PAH." (PMID 30925865, 2019).
triple-negative breast carcinoma (8 papers, 2015 to 2025). An invasive breast carcinoma which is negative for expression of estrogen receptor (ER), progesterone receptor (PR), and human epidermal growth factor receptor 2 (HER2). "In another study on triple-negative breast cancer where high expression of HDAC6 is linked to tamoxifen resistance, HDAC6 deacetylates the heat shock protein 90 (HSP90), essential for the correct folding of oncogenic proteins." (PMID 40284485, 2025). "In triple-negative breast cancer cells, HDAC6 inhibition or knockdown results in alterations to mitochondrial cristae structure, as detected by live-cell super-resolution STED nanoscopy and electron microscopy, along with the release of mitochondrial DNA." (PMID 40721560, 2025). "These experiments were carried out on an HCC38 triple-negative breast cancer cell line with stimulation over eighteen hours by erastin (ferroptosis inducer), tubacin (HDAC6 inhibitor) and combination of the two molecules (combo)." (PMID 38201582, 2023).